CTNNB1 (catenin beta 1)
Diseases named in the same sentence as CTNNB1 in open-access papers (continued):
Sharing a sentence is not in itself a finding about the gene and the disease.
tumor (continued). "In these cases, risk assignment differed between the tumour blocks due to intratumour heterogeneity in CTNNB1 mutation status and MMR protein expression." (PMID 28424422, 2017). "In this study, we detected that β-catenin was mutated in all neoplasms studied (100%), and that this frequency was higher than previously reported (approximate 90%), suggesting that CTNNB1 mutation is ubiquitous in SPT patients." (PMID 28054945, 2017). "Somatic mutations in genes encoding catenin beta 1 and vascular endothelial growth factor receptor 2 were identified in the patient’s tumor sample compared to the normal tissue." (PMID 28915721, 2017). "We describe the first report of parallel evolution of Wnt signalling in PC, where 3 separate gain-of-function mutations of β-catenin (CTNNB1) were identified in a single tumour." (PMID 28961847, 2017). "For CTNNB1, the prevalence across all tumor sites of primary carcinomas having at least one mutation was 3.6%." (PMID 29156750, 2017). "In thousands of primary carcinomas, we found that the prevalence of tumors with CDH1 or CTNNB1 mutations appear to be too low to explain most clinically-observed cases of cancer cell detachment from the primary tumor (i.e. regional or distant tumor spread)." (PMID 29156750, 2017). "For the first patient, prestudy tumor samples from lung metastases were revealed to be Akt1 (E17K) and CTNNB1 (G34V) mutation positive." (PMID 26931343, 2016). "It is well known that both APC and CTNNB1 mutation are frequently happened in CRCs and are critical for carcinogenesis and progression of CRCs, including tumor initiation and metastasis." (PMID 27880730, 2016). "The mutational status of the CTNNB1 exon 3 was determined for both parental tumor tissues and isolated cultured cells." (PMID 26686699, 2016). "This is further supported by our previous description of a patient with a germ line WT1 mutation who developed four tumors with different CTNNB1 mutations, suggesting their independent origin and/or tumor heterogeneity." (PMID 27213811, 2016). "Most notably, sHPC have been found to harbor frequent CTNNB1 mutations, ranking this tumor entity as a strong candidate for offering an equivalent to our mouse OE tumor-like lesions in human pathology." (PMID 27902722, 2016). "In patient 9’s plasma DNA (pre-treatment), we detected an additional mutation (CTNNB1 T41A) to the one found in the tumour." (PMID 27626278, 2016). "The primary tumor harbored a heterozygous c.121A>G/p.T41A CTNNB1 mutation, whereas the Wilms10 tumor cell culture carried a homozygous deletion of three nucleotides c.133-135 del TCT, leading to loss of amino acid S45 (p.S45Δ)." (PMID 27213811, 2016). "Other objectives are to investigate quality of life and to identify factors associated with tumor growth, in particular the relation with the presence of a CTNNB1-gene mutation in the tumor." (PMID 27565718, 2016). "The presence of different CTNNB1 mutations supports the sequential linear model whereby initiating mutations first occur in WT1, and for tumor development, additional CTNNB1 mutations are needed." (PMID 27213811, 2016). "The investigated CTNNB1 mutated APA lysates (n = 3) contained aldosterone at similar levels as KCNJ5 mutated tumor lysates (p = 0.48)." (PMID 26815163, 2016). "Secondary endpoints are quality of life and the rate of influence on tumor progression for several factors, such as CTNNB1-mutations, age and localization." (PMID 27565718, 2016).
tumor (continued). "A synergistic effect of PTEN loss and WNT/CTNNB1 signaling pathway activation has been reported in tumor development and progression." (PMID 27281609, 2016). "To assess the role of β-catenin function in another Apc mutation-dependent tumor model, we explored the role of Ctnnb1 gene dosage in a mouse model of ovarian endometrial adenocarcinoma (OEA) arising from bi-allelic inactivation of both the Apc and Pten genes." (PMID 26528816, 2015). "Gain of 3p22.1 in Patient 4 included CTNNB1, a gene that encodes β-catenin and an essential participant of the Wnt signaling pathway whose deregulation is critical for tumor development." (PMID 26317783, 2015). "One of the interesting findings of the paper is that, in tumours harbouring CTNNB1 mutation, there was downregulation of miR-16 and miR-141." (PMID 26064134, 2015). "Altogether 76 tumours were analyzed and molecular subtypes were identified by immunohistochemistry using representative antibodies, detection of chromosome 6 monosomy and CTNNB1 mutation." (PMID 25862008, 2015). "Of 22 tumors that showed nuclear accumulation of β-catenin in >5 % of tumor cells, CTNNB1 mutation status was available for all 22, and subgroup information was available for 19 samples." (PMID 24791927, 2014). "Concordance between tumor cellularity and CTNNB1/β-catenin mutation prevalence detected by deep sequencing in five solid pseudopapillary tumors (SPT)." (PMID 25127237, 2014). "MEL9 is characterized by both NRAS and BRAF mutations in founding clone, along with a CTNNB1 P16S mutation that arose later in the evolution of the tumor." (PMID 25393105, 2014). "The CTNNB1 gene mutation was detected in all samples; moreover, the allelic frequency of CTNNB1 mutation was consistent with the percentage of tumor cells as scored by the pathologists." (PMID 25127237, 2014). "Studies have suggested that the site of the CTNNB1 mutation is associated with differences in clinical behavior of the tumor 6,10,14." (PMID 24402778, 2014). "Of the 309 unique, validated mutations identified through sequencing of the TCGA GBM tumor samples, CTNNB1, EP300, STAT3, and TOP1 also appear in the 50-gene subnetwork signature." (PMID 24068912, 2013). "Tumours with a dMMR were characterized by lower degrees of activation of CTNNB1 (p = 0.02) and the presence of c.1799 T > A mutation in the BRAF gene (p = 0.05)." (PMID 23446022, 2013). "The smaller subset is characterized by loss of the WT1 tumour suppressor gene often together with oncogenic mutations in CTNNB1, the gene encoding β-catenin, and these tumours tend to be found associated with intralobar nephrogenic rests." (PMID 23239670, 2013). "The class of verified anti-apoptotic molecules overexpressed in cancer includes prominent tumor-associated proteins such as β-Catenin (CTNNB1), Osteopontin (OPN/SPP1), BMI1, Peroxiredoxin 3 (PRDX3;) and DAD1." (PMID 23717670, 2013). "Since CTNNB1 is a key downstream mediator in the Wnt signaling pathway, and an increase in active CTNNB1 has been linked to tumor proliferation and metastasis, we next investigated the role of SUMOylation on ATF3-mediated CTNNB1 expression." (PMID 23591848, 2013).
tumor (continued). "CTNNB1 mutations were rare, with one CTNNB1 mutation identified in a Group 1A tumor and one in a Group 1B tumor." (PMID 22470196, 2012). "Having ruled out direct APC mutations, we focused on potential APC-activating mutations of the β-catenin gene CTNNB1, which have been identified as a frequent event in various tumour entities." (PMID 22919349, 2012). "Only one tumour displaying cytoplasmic CTNNB1 staining had a loss of one copy of chromosome 6 (S Miller, unpublished data)." (PMID 19293793, 2009). "In the CNS PNET cohort, only one of the 26 primary tumours sequenced contained a mutation in exon 3 of CTNNB1 (4%)." (PMID 19293793, 2009). "We found four missense mutations of the CTNNB1 gene in three tumours: Pro44Ala (CCT to GCT) and Ser45Pro (TCT to CCT) in #11, Thr41Ala (ACC to GCC) in #21, and Ser45Tyr (TCT to TAT) in #35." (PMID 16909133, 2006). "Abrogation of the WNT pathway by CTNNB1 mutations, resulting in reduced serine/threonine phosphorylation, has been recognised as playing an important role in the development of many tumours." (PMID 16909133, 2006). "Tumours from KrasG12D-primed mice showed the smallest range of O/E ratios; combined with the high tumour multiplicity observed in these mice, this finding indicates that expression of KrasG12D creates a broadly permissive transformation landscape for Ctnnb1-activating mutations." (PMID 41339549, 2026). "Under the process of cell clonal evolution in Arid1a‐deficient liver tissues, cells with Ctnnb1 mutations may further expand and promote tumor formation." (PMID 41133886, 2026). "In contrast, the higher proportion of missense mutations in H/L patients, particularly within SMAD2 and CTNNB1, may result in more nuanced functional alterations that contribute to tumor progression through different biological mechanisms." (PMID 40869017, 2025). "Three tumours harboured pathogenic or likely pathogenic CTNNB1 alterations." (PMID 41263790, 2025). "A recent study identified six ACP tumor cell subsets based on CTNNB1 mutation status." (PMID 40575267, 2025). "Since the specific CTNNB1 variant seen in this tumor, p.I35T, has been reported in up to 80% of basal cell adenomas, this case may actually represent a basal cell adenoma presenting in infancy." (PMID 40906279, 2025). "Somatic mutations in exon 3 of CTNNB1 were detected in 5 of the 29 HCC tumour samples (17.2%)." (PMID 40650279, 2025). "Taken together, our findings strongly suggest that for 30/32 BCA cases (93.7%), activation of the Wnt/β-catenin signalling pathway, either through mutation of CTNNB1 at p.I35T or FBXW11 at p.F517S is the primary mechanism of tumourigenesis in this tumour entity." (PMID 40389436, 2025). "In prior studies, β‐catenin has been implicated in promoting tumour invasiveness, and the upregulation of CTNNB1 in our experimental group suggests a complex interaction where the intervention may mitigate the pro‐invasive effects of β‐catenin." (PMID 40111872, 2025). "Furthermore, previous reports have indicated that tumor-infiltrating lymphocytes (TILs) are insuffificiently primed by antigen-presenting cells in CTNNB1 mutated animal tumor models." (PMID 41227323, 2025).
tumor (continued). "The majority of colorectal cancer CRCs exhibit genetic changes in the WNT pathway, such as APC mutations, activating mutations in CTNNB1 (β-catenin), etc., which could encourage the initial growth of the tumor." (PMID 40240755, 2025). "The findings of GNA11/Q single mutations in hyperplastic regions adjacent to double-mutant APAs indicate that GNA11/Q mutations may arise prior to CTNNB1 mutations in the development of these tumours." (PMID 40725432, 2025). "CTNNB1 mutations are associated with advanced disease stages, high tumor grade, and poor prognosis." (PMID 40072110, 2025). "Mutations in CTNNB1 may also promote cancer stem cell characteristics that are thought to be responsible for tumor recurrence and metastasis." (PMID 40072110, 2025). "CTNNB1 regulates cell proliferation and differentiation through the Wnt signaling pathway, and its mutations can lead to uncontrolled cell proliferation, suppressed apoptosis, and activation of tumor invasion and metastasis." (PMID 40150405, 2025). "At 8.3-weeks post-HDTVi, there was an increase in gross tumor burden and significant increase in liver weight, LW/BW, and spleen weight in β-M-POU2F1 + αCD3 versus β-M-POU2F1 + IgG animals, suggesting an immune-dependent role for POU2F1-mediated tumor regression in CTNNB1-mutated HCC." (PMID 40442146, 2025). "However, the prognostic significance of CTNNB1 mutations can vary depending on the tumor subtype and other molecular features." (PMID 40072110, 2025). "Additionally, circulating tumor DNA (ctDNA), specifically mutations in CTNNB1, has demonstrated considerable diagnostic potential." (PMID 40136353, 2025). "Around 50% of all patients experienced spontaneous regression either as the first event or following progression, and initial tumor size, tumor location, and CTNNB1 mutation status were consistently associated with the probability of spontaneous tumor regression." (PMID 39620931, 2025). "A KRAS mutation and a CTNNB1 mutation were identified in the tumor." (PMID 39939466, 2025). "In addition to the constitutional DICER1 p.(Tyr1357fs*18) variant, the somatic DICER1 p.(Asp1910Tyr) oncogenic variant and the somatic CTNNB1 p.(Thr41Ala) oncogenic variant were also identified in this tumor." (PMID 40892116, 2025). "Additionally, ctDNA, specifically CTNNB1 mutations, is a sensitive marker for tumor burden and treatment response, while SUA serves as a promising prognostic tool, correlating with advanced tumor stages and poor treatment responses." (PMID 40136353, 2025). "In EECs with CTNNB1 mutations, such therapies may inhibit tumor growth and invasiveness by blocking downstream oncogenic signals." (PMID 40072110, 2025). "Furthermore, NGS for tumor protein 53, SMAD4, mammalian target rapamycin, and CTNNB1 genes are useful in identifying advanced neoplasia when combined with GNAS/MAPK mutation with a sensitivity and specificity of 88% and 98%, respectively." (PMID 38731128, 2024). "However, it is important to note that two-thirds of CTNNB1-mutated tumours are associated with the Excluded subclass, described as devoid of immune cell infiltrates, while the other third is associated within inflamed class." (PMID 39261716, 2024). "A Japanese early clinical experience explored the effect of Atezolizumab plus Bevacizumab (ATZ/BV) in HCC patients harbouring CTNNB1 Mutation and found that ATZ/BV might improve the immunosuppressive tumour microenvironment caused by CTNNB1 mutation." (PMID 38825709, 2024). "Somatic variants in APC and CTNNB1 were unique to each tumor." (PMID 38725616, 2024). "However, mutations in the CTNNB1 gene within tumor cells result in the intracellular accumulation of β-catenin molecules." (PMID 39567475, 2024).
tumor (continued). "It remains uncertain whether CTNNB1 mutations cause autonomous aldosterone production or tumor-like behavior of the APAs." (PMID 39429164, 2024). "Interestingly, at 8.3-weeks post-HDTVi, there was a significant increase in tumor burden in β-M-POU2F1 + βCD3 versus β-M-POU2F1 + IgG animals, suggesting an immune-dependent role for POU2F1-mediated tumor regression in CTNNB1-mutated HCC." (PMID 39711542, 2024). "CTNNB1/SOX4 expression in CRC tumors was significantly associated with tumor-infiltrating CAFs." (PMID 38203779, 2024). "Whereas N-nitrosodiethylamine (DEN) carcinogen induced liver tumours without detectable ß-catenin mutations, the addition of phenobarbital as a tumour promoter induced a strong selective pressure allowing the emergence of CTNNB1-mutated HCC in about 80% of mice." (PMID 39261716, 2024). "CTNNB1-mutated tumours were described by several studies as well-differentiated." (PMID 39261716, 2024). "The same Ctnnb1 S37P mutation was found in five organoid lines derived from the same tumor (586T2), indicating this mutation may be an early clonal event." (PMID 37746286, 2023). "Ctnnb1 mutation in tumor organoids was further examined via Sanger sequencing." (PMID 37746286, 2023). "The association between tumor size and CTNNB1 mutation was explored by χ2 analysis." (PMID 35166264, 2023). "Overall, CTNNB1 mutation causes aberrant β-catenin signaling to contribute to tumor aggressiveness." (PMID 36674932, 2023). "However, the effectiveness of focusing on upstream targets is still debatable due to tumor resistance with more downstream alterations, including CTNNB1- or APC-mutated malignancies." (PMID 37577746, 2023). "A meta‐analysis study showed that dysregulation of CTNNB1 may be associated with tumour progression and poor prognosis in patients with GC." (PMID 37118990, 2023). "However, several studies demonstrated that mutation of CTNNB1 have also been associated with scarcity of immune cells in the tumor microenvironment and poor clinical response to immune checkpoint inhibitor therapy." (PMID 37733676, 2023). "Also, β-catenin is a multifunctional protein encoded by the CTNNB1 gene that mediates signal transduction and exerts a core role in promoting tumor proliferation and metastasis in various malignancies." (PMID 36739418, 2023). "This is supported by the detection of CTNNB1 mutations in every tumor that was tested." (PMID 37174013, 2023). "Future experiments that are conducted at a larger scale can help distinguish whether specific CTNNB1 variants yield a difference in tumor and stroma surface protein expression." (PMID 37377751, 2023). "In this study, CTNNB1 mutation led to abnormally low expression of some genes, suggesting that ARGs are likely to be regulated by mutations in major tumour suppressors or tumour-promoting genes, and hence, may promote tumour progression." (PMID 36844873, 2023). "CTNNB1 was initially described as a potential tumor suppressor gene as somatic Ctnnb1 deletion or mutation, which is accompanied by loss of gene expression, is linked to tumor development in a variety of cancers." (PMID 37009120, 2023). "CTNNB1 mutation status and tumor size could be used to identify patients with risk of failure of AS." (PMID 35166264, 2023).